DDIT4 (DNA damage inducible transcript 4)
Description:
Regulates cell growth, proliferation and survival via inhibition of the activity of the mammalian target of rapamycin complex 1 (mTORC1). Inhibition of mTORC1 is mediated by a pathway that involves DDIT4/REDD1, AKT1, the TSC1-TSC2 complex and the GTPase RHEB. Plays an important role in responses to cellular energy levels and cellular stress, including responses to hypoxia and DNA damage. Its role in the response to hypoxia depends on the cell type; it mediates mTORC1 inhibition in fibroblasts and thymocytes, but not in hepatocytes (By similarity). Required for mTORC1-mediated defense against viral protein synthesis and virus replication (By similarity). Inhibits neuronal differentiation and neurite outgrowth mediated by NGF via its effect on mTORC1 activity. Required for normal neuron migration during embryonic brain development. Plays a role in neuronal cell death.
Synonyms: REDD-1; REDD1; RTP801; FLJ20500; Dig2
Tractability: PROTAC: UniProt records ubiquitination sites on it; ubiquitination databases record sites on it.
Gene: Protein-coding gene on chromosome 10 (72,273,919 to 72,276,039, forward strand). Ensembl gene ENSG00000168209.
Subcellular location: Mitochondrion; Cytoplasm, cytosol
Subcellular location (Human Protein Atlas): Cytosol
Gene Ontology:
Molecular function: protein binding; 14-3-3 protein binding
Biological process: defense response to virus; negative regulation of TOR signaling; response to hypoxia; apoptotic process; brain development; intracellular signal transduction; neuron differentiation; neuron migration; neurotrophin TRK receptor signaling pathway; negative regulation of signal transduction
Cellular component: cytoplasm; cytosol; mitochondrion
Genetic constraint (gnomAD): Loss-of-function variants: 20 observed, 19.69 expected, observed/expected ratio (o/e) 1.02, 90% interval 0.71 to 1.48. The upper end of that interval is the gene's LOEUF score, 1.48, which puts it in group 6 of 6, group 1 being the genes least tolerant of losing a copy. Missense variants: 316 observed, 313.07 expected, observed/expected ratio (o/e) 1.01, 90% interval 0.92 to 1.11. Synonymous variants: 152 observed, 153.9 expected, observed/expected ratio (o/e) 0.99, 90% interval 0.87 to 1.13.
Homologues: Orthologues: chimpanzee DDIT4 (99% identical), macaque DDIT4 (98% identical), pig DDIT4 (93% identical), rabbit DDIT4 (92% identical), mouse Ddit4 (91% identical), rat Ddit4 (91% identical), guinea pig DDIT4 (90% identical), dog DDIT4 (78% identical), tropical clawed frog ddit4 (54% identical), zebrafish ddit4 (44% identical), Drosophila melanogaster chrb (19% identical), Drosophila melanogaster scyl (19% identical). Paralogues in human: DDIT4L (25% identical).
Diseases named in the same sentence as DDIT4 in open-access papers:
DDIT4 is named in the same sentence as 194 diseases in open-access papers, as found by Europe PMC text mining. Sharing a sentence is not in itself a finding about the gene and the disease. The quoted sentences say what the papers report.
breast cancer (41 papers, 2009 to 2025). A primary or metastatic malignant neoplasm involving the breast. "DDIT4 is associated with several cancers, including melanoma, leukemia, breast cancer, and lung cancer." (PMID 38079253, 2024). "High levels of Klhl24, Hbp1, Crebrf, Ypel2, CD22 and Ypel3 were correlated with better outcomes, whereas lower levels of Gdf15, Cdc25a, Ddit4 and Psat1 were associated with better prognosis in breast cancer patients." (PMID 34990474, 2022). "In contrast, lower levels of the mRNAs for Gdf15, Cdc25a, Ddit4 and Psat1 were associated with better prognosis in breast cancer patients." (PMID 34990474, 2022). "DDIT4 is expressed in breast cancer and is associated with a poor prognosis in various cancers including breast cancers." (PMID 33075093, 2020). "High levels of DDIT4 were significantly associated with a worse prognosis in acute myeloid leukemia, breast cancer, glioblastoma multiforme, colon, skin and lung cancer." (PMID 28484222, 2017). "Recent analyses of DDIT4 in several cancer types have shown that high expression of this gene is associated with poor prognosis in several hematological and solid tumors, such as acute myeloid leukemia, breast cancer and lung cancer." (PMID 40276062, 2025). "For example, in breast cancer, DDIT4 overexpression was significantly related to a poor prognosis in the basal subtype, while there is no such correlation in the HER2‐enriched subtype." (PMID 40621878, 2025). "It increases miR-495 in breast cancer initiating cells, and it promotes oncogenesis by the down-regulation of DDIT4." (PMID 38079253, 2024). "The DDIT4 transcription levels in breast cancer samples were significantly higher than those in normal samples." (PMID 37391802, 2023). "TIMER data revealed that the mRNA expression of DDIT4 was significantly higher in breast cancer tissues than in normal tissues." (PMID 37391802, 2023). "In particular, TCGA data indicated a higher expression of DDIT4 in TNBC than in other subtypes of breast cancer." (PMID 37391802, 2023). "Previously, TRIB3 was shown to be induced by hypoxia (0.1–0.5% O2) in breast cancer cells and in rat pulmonary artery smooth muscle cells (5% O2), Expression of Ddit4 and Gadd45a were previously shown to be increased under hypoxia and oxidative stress." (PMID 37656229, 2023). "We also analyzed the correlation between the DDIT4 transcription level and immune cell infiltration in breast cancer." (PMID 37391802, 2023). "Overall, the findings imply that the mRNA expression of DDIT4 was significantly correlated with the poor prognosis of patients with breast cancer and TNBC." (PMID 37391802, 2023). "In this paper, Ddit4 is described as a prognostic biomarker in several malignancies including breast cancer." (PMID 34990474, 2022). "Most malignant carcinomas such as myeloid leukemia, colon, skin, head and neck carcinoma, and breast carcinoma present high, sustained, constitutive expression of DDIT4 with poor prognosis." (PMID 34565301, 2021). "More importantly, DDIT4 is described as an independent indicator for a poor prognosis in several malignancies, such as acute myeloid leukemia, breast cancer, glioblastoma multiforme, colon, skin and lung cancer." (PMID 32982585, 2020). "DDIT4 also acts as a pro-death transcript in the calcitriol inducing endoplasmic reticulum -stress-like response in breast cancer." (PMID 32497068, 2020). "In breast cancer, DDIT4 acts as a tumor-suppressor to regulate miR-495-mediated oncogenesis and hypoxia resistance." (PMID 29976242, 2018). "Melatonin enhances arsenic trioxide-induced cell death via sustained upregulation of DDIT4 expression in breast cancer cells." (PMID 29976242, 2018).
breast cancer (continued). "Several works have described an involvement of DDIT4 in the breast cancer biology, while its expression seems to have different patterns among breast cancer subtypes." (PMID 29707520, 2018). "On the other hand, DDIT4 evaluation in the SurvExpress platform showed that DDIT4 expression was related to a poor prognosis (in terms of RFS) in 3 out of 15 breast cancer datasets (Vant Veer Nature, GSE4922 and GSE19615)." (PMID 28484222, 2017). "The involvement of some of the genes affecting cancer cell death–Adm, Cflar, Cyr61, Ddit4, Itgb1, Mapk1, Mapk8, Tgfβ2, Tpm1, Vegfα and Wasf1, was demonstrated in breast cancer cell lines." (PMID 19450255, 2009). "To gain additional insights into the biological significance of DDIT4, we investigated the potential role of DDIT4 in breast cancer by analyzing the mRNA sequencing data of 1093 patients with breast cancer, obtained from the TCGA database, using the LinkFinder module in LinkedOmics." (PMID 37391802, 2023). "However, functional studied are needed to further investigate the precise mechanisms by which the products encoded by DDIT4 hub genes mediate resistance to chemotherapy and immunotherapy and to further confirm whether these hub genes are the potential indicators of worse prognosis in breast cancer." (PMID 37391802, 2023). "Further, DDIT4 overexpression was associated with worse OS (HR = 1.34 (1.11–1.62), p < 0.01), PPS (HR = 1.43 (1.13–1.8), p < 0.01), DMFS (HR = 1.3 (1.12–1.52), p < 0.001), and RFS (HR = 1.5 (1.35–1.66), p < 0.001) in breast cancer." (PMID 37391802, 2023). "When the pooled dataset was stratified according to the molecular subtype of breast cancer, the logrank test indicated that DDIT4 expression over the median was significantly related with a poor prognosis in Luminal A (P = 0.03); Luminal B (P = 0.01) and in the Basal subtype (P = 3.8 × 10−7)." (PMID 28484222, 2017). "A correlation between DDIT4 expression and poor survival was found in specific tumor types including ovarian cancer, breast cancer, lung cancer, and bladder urothelial carcinoma, which suggests that DDIT4 may be a cancer related protein and potential biomarker." (PMID 37391802, 2023). "A recent in silico analysis of DDIT4 expression in several cancer types showed that the high expression of this gene was related to a bad outcome in diverse hematologic and solid tumors, such as acute myeloid leukemia, breast cancer, glioblastoma multiforme, melanoma, lung, and colon cancer." (PMID 29707520, 2018). "The anticancer activities of baicalein have been attributed to a variety of mechanisms that are important in breast cancer, including inhibiting 12-LOX activity, upregulating DDIT4 expression, inhibiting mTOR, and suppressing the aromatase (CYP19) activity and thus decreasing estrogen biosynthesis." (PMID 28060756, 2017). "Furthermore, a recent study reported that baicalein inhibited tumor growth in vivo via upregulation of DNA-damage-inducible transcript 4 (DDIT4) expression, which mediated the inhibition of mTOR in a breast cancer xenogeneic mouse model." (PMID 27735841, 2016). "The formation of breast cancer CSCs was accompanied with transcriptional repression of three mTOR suppressors (PKAA1, DDIT4/REDD1, and deptor) as well as upregulation of phosphorylated S6K protein levels, again signifying the activation of mTOR pathway in the acquisition of CSC-like cellular states." (PMID 27826244, 2016). "In addition, the heatmaps showed the top 50 important genes exhibiting positive and negative co-expression with DDIT4 in breast cancer." (PMID 37391802, 2023).
breast cancer (continued). "Second, we observed a significant upregulation of the gene DDIT3, but not DDIT4, after BB-CLA treatment in both feline and canine mammary cancer cell lines, which could indicate that BB-CLA is promoting activation of the apoptosis pathway rather than the autophagy pathway in response to ER stress." (PMID 29649984, 2018).
gastric cancer (25 papers, 2017 to 2025). A primary or metastatic malignant neoplasm involving the stomach. "Conversely, a high DDIT4 expression was associated with an improved prognostic in gastric cancer." (PMID 28484222, 2017). "Fn1 and JamL serve as prognostic biomarkers for breast and thyroid cancers, lung adenocarcinoma, and gastric cancer, while Ddit4 is a potential prognostic biomarker for colorectal cancer 27-32." (PMID 40206211, 2025). "Previous studies have reported that DDIT4 facilitates the proliferation, migration, and drug resistance of several cancers, including glioma, gastric cancer, and lung cancer." (PMID 39201624, 2024). "Evidence from several recent studies has indicated that the overexpression of DDIT4 is also an adverse factor in ovarian carcinoma, gastric cancer, and lung adenocarcinoma." (PMID 37391802, 2023). "Compared with normal tissues, high expression of DDIT4 was observed in a variety of tumor tissues, such as colorectal cancer, glioma, head and neck squamous cell carcinoma, and gastric cancer." (PMID 37715019, 2023). "Previously, DDIT4 has been registered to exert a pivotal part in the proliferation and tumorigenesis of gastric cancer." (PMID 32982585, 2020). "DDIT4 was shown to accelerate growth of gastric cancer cells through upregulation of MAPK." (PMID 37016335, 2023). "On the contrary, increased DDIT4 expression was associated with an improved prognosis in gastric cancer but was not related to clinical outcome of ovarian cancers." (PMID 34045534, 2021). "DNA damage inducible transcript 4 (DDIT4) could promote gastric cancer proliferation and tumorigenesis through the MAPK pathways." (PMID 34663825, 2021). "Overexpression of DDIT4 could accelerate the proliferation and tumorigenesis of gastric cancer." (PMID 36768316, 2023). "In addition, DDIT4 silencing in SGC7901 cells attenuated gastric cancer cell S phase arrest." (PMID 29976242, 2018). "In the present study, we examined DDIT4 expression levels in GC tissue samples and cell lines, and investigated the role of DDIT4 and the mechanism by which it is dysregulated in gastric cancer." (PMID 29976242, 2018). "Taken together, our results suggest that DDIT4 may function as an oncogene in gastric cancer, providing a promising therapeutic strategy for GC treatment." (PMID 29976242, 2018). "Conversely, DDIT4 expression over the median was a strong protective factor in a pool of gastric cancer datasets, although it could not be corroborated with the TCGA data." (PMID 28484222, 2017).
lung carcinoma (25 papers, 2017 to 2025). "Fluorescence in situ hybridization (FISH) and IF experiments on lung cancer tissues and adjacent tissues confirmed that S. pneumoniae and DDIT4 were enriched and highly expressed in lung cancer tissues, and high expression of DDIT4 was associated with poor prognosis of LUAD patients." (PMID 36601406, 2022). "As a result, we found that DDIT4 promoted the proliferation, migration, and invasion of lung cancer cells." (PMID 37715019, 2023). "We identified similarities and differences in the tumor cell and tumor microenvironment between lung adenocarcinoma and brain metastasis and elucidated that DDIT4 plays an important role in the process of lung cancer metastasis." (PMID 37715019, 2023). "The results showed that the expression of DDIT4 and the enrichment of S. pneumoniae were significantly higher in lung cancer tissues than in paracancerous tissues." (PMID 36601406, 2022). "Third, we found that S. pneumoniae infection enhanced DDIT4 expression and promoted the migration and invasion of lung cancer cells in vitro by up-regulating the AKT pathway." (PMID 36601406, 2022). "At the end of this study, we used IF combined with FISH to detect the expression of DDIT4 and the enrichment of S. pneumoniae in lung cancer tissues." (PMID 36601406, 2022). "After that, we verified the utility of the DDIT4 gene as a prognostic marker of lung cancer in the TCGA database (1133 cases)." (PMID 34659532, 2021). "We further searched the TCGA database and found that DDIT4 is correlated with the prognosis of lung cancer, especially in LUAD patients." (PMID 34659532, 2021). "DDIT4 was involved in the survival-related autophagy of cancer cell and affected targeted therapy for lung cancer." (PMID 34007269, 2021). "Finally, we experimentally validated that the downregulation of DDIT4 inhibited the proliferation, migration, and invasion of lung cancer cells." (PMID 37715019, 2023). "Finally, we found that the downregulation of DDIT4 significantly inhibited the proliferation of lung cancer cells PC9 and A549." (PMID 37715019, 2023). "Taken together, we hypothesized that DDIT4 plays a key role in the process of lung cancer metastasis." (PMID 37715019, 2023). "The data provided by this study show that S. pneumoniae enriched in the lower airway of patients with lung cancer can up-regulate DDIT4 expression and subsequently activate the mTORC2/AKT signal pathway, thereby increasing the migration and invasion abilities of A549 cells." (PMID 36601406, 2022). "We also assessed PML and DDIT4 mRNA expression correlations by cancer cell tissue type and found significant (p < 0.05) and strong correlations (Spearman’s r = 0.275–0.345) in breast, ovarian and lung cancer cells." (PMID 28332630, 2017). "Thus, our results revealed that DDIT4 plays a crucial role in the metastasis of lung cancer." (PMID 37715019, 2023). "The remaining DEGs, DDIT4 and ANGPTL4, were recently identified as candidate genes for the prediction of survival outcomes in lung cancer and OvCa patients." (PMID 37444459, 2023). "Therefore, DDIT4 could be a potential target for the treatment of lung cancer metastasis." (PMID 37715019, 2023). "Meanwhile, S. pneumoniae could deteriorate an inflammation condition by upregulating the expression of DNA damage inducible transcript 4 (DDIT4), which further activates the AKT pathway and enhances the migration and invasion of lung cancer cells." (PMID 38542056, 2024). "Since the strongest correlation between DDIT4 and PML expression occurred in lung cancer derived cell lines, and specifically lung adenocarcinoma (Spearman’s 0.399, p < 0.01), we extended our analysis to lung cancer subtypes." (PMID 28332630, 2017). "However, in lung cancer cells, the SIRT1/2-specific inhibitor salermide upregulates pro-survival autophagy via HSPA5 acetylation and subsequent activation of activating transcription factor 4 (ATF4) and DNA damage inducible transcript 4 (DDIT4) to inhibit the mTOR signaling pathway." (PMID 36646695, 2023).